SYK (spleen associated tyrosine kinase)
Diseases named in the same sentence as SYK in open-access papers (continued):
Sharing a sentence is not in itself a finding about the gene and the disease.
COVID-19 (13 papers, 2020 to 2026). A disease caused by infection with severe acute respiratory syndrome coronavirus 2. "Given the critical role of SYK in FcγR signaling, blocking SYK activity could serve as a potential therapeutic for severe COVID-19 by ceasing the pathogenic hyperactivation of immune cells and the ensuing endotheliopathy." (PMID 37699657, 2023). "Although our data suggest SYK inhibitors are promising candidates for COVID-19 therapeutics, targeting other kinases in the FcγR signaling cascade did not yield similar results." (PMID 37699657, 2023). "SYK also plays an important role in the treatment of COVID-19 and has been reported to regulate signal transduction pathways implicated in these complications associated with COVID-1952." (PMID 37037848, 2023). "R406 is the active ingredient of the SYK inhibitor, fostamatinib, which suppresses NETosis in neutrophils from healthy donors when activated by COVID-19 patient plasma." (PMID 35309344, 2022). "For example, antigen–antibody complexes can stimulate FcγRIIA receptors on neutrophils to induce NETs in COVID-19 via spleen tyrosine kinase (SYK) phosphorylation and downstream signaling." (PMID 35309344, 2022). "The therapeutic potential of targeting SYK was demonstrated in a recent study showing that the SYK inhibitor fostamatinib mitigated myeloid proinflammatory responses believed to contribute to the immunopathogenesis of severe COVID-19." (PMID 38389037, 2024). "In conjunction with additional emerging evidence indicating the beneficial effect of another SYK inhibitor fostamatinib, our work provides evidence for pursuing clinical trials to investigate repurposing entospletinib for counteracting COVID-19 pathology in severely ill patients." (PMID 37699657, 2023). "Fostamatinib’s inhibition of SYK plays a crucial role in reducing pro-inflammatory cytokine release, neutrophil extracellular trap production, and platelet aggregation, offering potential relief from organ dysfunction in critically ill COVID-19 patients." (PMID 38187394, 2023). "In this connection it is important to point out that urine proteomic analysis of COVID-19 patients has shown a significant downregulation of SYK which is involved in dectin 1 and dectin 2 mediated signalling mechanisms in innate immune cells against fungal infections." (PMID 35111359, 2022). "Furthermore, recent data suggested a potential role of SYK-BTK inhibition in preventing thrombosis during COVID-19." (PMID 32796683, 2020). "Although both tested SYK inhibitors can dampen anti-spike-induced inflammation, compared with R406, our data indicate that entospletinib has less effect on the macrophage anti-viral response, thereby representing a promising therapeutic approach for COVID-19 treatment." (PMID 37699657, 2023). "In addition, the effect of enoxaparin on antithrombin III associated with inflammatory genes (e.g., SYK or PAD4) has not been investigated in COVID-19 patients." (PMID 35563204, 2022). "Compared to the HC group, several TPKs in the plasma of PLWH with COVID-19 were significantly downregulated, including BTK, SYK, and TEC." (PMID 40568587, 2025). "We observed that the COVID-19 ICU patients had activated T cell and B cell signaling characterized with activation of the tyrosine kinases LCK, LYN, and SYK." (PMID 38389037, 2024). "The results demonstrated that the levels of PAD4, RELA, PKC, SYK and ERK gene expression were signifFicantly increased after healthy neutrophils were incubated with the plasma of COVID-19 patients (p < 0.05)." (PMID 35563204, 2022). "Previous studies have also indicated that SYK and JAK2 may serve as target proteins related to COVID-19." (PMID 37037848, 2023). "Notably, compounds targeting SYK and PI3K activity provide potential treatment avenues for severe COVID-19, specifically addressing inflammation induced by anti-spike immune complexes." (PMID 38187394, 2023).
COVID-19 (continued). "Its effects through SYK have been shown before as interfering with thrombosis but not with hemostasis and its potential use in COVID-19 has also been suggested by a computational study that confirmed fostamatinib’s targets by molecular docking." (PMID 38187394, 2023). "Moreover, the upregulated genes (PAD4, RELA, PKC, SYK, and ERK) after incubation with COVID-19 plasma were significantly decreased by enoxaparin pretreatment." (PMID 35563204, 2022). "As both SYK inhibitors fostamatinib and entospletinib are capable of blocking phagocytosis, whether these compounds can curb SARS-CoV-2 uptake and subsequent pyroptosis in COVID-19 is of interest for further exploration." (PMID 37699657, 2023). "Therefore, interventions targeting SYK and PI3K activity might provide potential treatment options for severe COVID-19." (PMID 37699657, 2023). "Indeed, the authors speculated that SYK-BTK inhibition may block platelet-activating receptor (CLEC-2) and may reduce microvascular and venous thrombosis in COVID-19 patients." (PMID 32796683, 2020).
asthma (12 papers, 2012 to 2025). "Our results indicate that the differential expression of the miRNAs in dust mite-induced pediatric asthma may regulate their target gene SYK and may have an impact on the PI3K-AKT pathway associated with the production of cytokines." (PMID 30406061, 2018). "SYK has been found to be altered in DNA, mRNA and protein expression in asthma patients among Pakistani population therefore patients should be treated according to their Syk status for more effective recovery." (PMID 31531378, 2019). "SYK Inhibitors block spleen tyrosine kinase (SYK), reducing mast cell-mediated inflammation and improving asthma control." (PMID 40337626, 2025). "Methyl rosmarinate (degree, 8; betweenness centrality, 0.02733; closeness centrality, 0.4715) also shared the same targets (STAT3, PIK3CB, MAPK1, ESR1, SYK, and EGFR) and identical asthma-related signaling pathways with caffeic acid." (PMID 35572723, 2022). "Meanwhile, SYK and EGFR were taken grant for modulating the progress of asthma by function in PI3K pathway and influence on cell differentiation, T or B cell and so on." (PMID 30406061, 2018). "This suggests that miRNA-27b-3p may have a regulatory function involved in the degradation or inhibition of SYK and EGFR in the asthma group(s)." (PMID 30406061, 2018). "In our study, we have found that there are significant differences in the expression of genes (SYK, PI3K, and EGFR) and the concentration of cytokines between dust mite-induced asthma and healthy controls, suggesting that EGFR, SYK, and PI3K may be involved in dust mite-induced pediatric asthma." (PMID 30406061, 2018). "Thus, it appears that the expression of these gene (SYK, EGFR, PI3K), which are involved in the PI3K-AKT pathway, may be connected with the secretion level of cytokine in asthma, especially in dust-mite induced pediatric asthma." (PMID 30406061, 2018). "Finally, inhibitors of non-RTKs, such as stem cell growth factor receptor (c-kit), spleen tyrosine kinase (SYK), the proto-oncogene tyrosine-protein kinase Src, and Janus kinase (JAK), have also been investigated in rodent models of asthma but have not yet progressed to studies in humans." (PMID 29904584, 2018).
diffuse large B-cell lymphoma (12 papers, 2015 to 2025). "Recently, four unique monoallelic gain-of-function SYK variants were identified in six patients with hypogammaglobulinemia, multiorgan inflammatory disease and diffuse large B-cell lymphoma." (PMID 41114848, 2025). "Recently, four heterozygous variants in SYK were reported to cause hypogammaglobulinemia, multiorgan inflammatory disease and diffuse large B-cell lymphoma." (PMID 41114848, 2025). "In contrast to this, SYK activation through the Fc receptors of B cells has been observed to induce apoptosis in DLBCL (diffuse large B cell lymphoma)." (PMID 38473324, 2024). "Further studies are needed to determine the role of PKA in the regulation of SYK by cAMP in diffuse large B-cell lymphoma cell." (PMID 38233872, 2024). "There is also evidence of cross-communication with the BCR pathway triggered by mutated MyD88 through the activation of the BCR-signaling component SYK (spleen tyrosine kinase) in WM and activated B-cell diffuse large B-cell lymphoma (ABC DLBCL) cells." (PMID 35628381, 2022). "It remains unclear how cAMP inhibits SYK in diffuse large B-cell lymphoma cell." (PMID 38233872, 2024). "In several hematological malignancies, such as CLL, diffuse large B-cell lymphoma (DLBCL), mantle cell lymphoma (MCL) and follicular lymphoma (FL), SYK acts as a proto-oncogene and is thus involved in tumorigenesis." (PMID 33435587, 2021). "In addition, cAMP can induce diffuse large B-cell lymphoma cell apoptosis by inhibiting spleen tyrosine kinase (SYK)/PI3K/AKT pathway, which is independent of PKA and EPAC." (PMID 38233872, 2024).
fungal infection (12 papers, 2016 to 2025). "Overall, our study first reported that SYK was modified through K27-linked polyubiquitination by TRIM31 upon fungal infection, and also uncovered its significance in positively regulating the activation of SYK-associated signaling cascades and the resultant anti-fungal immunity." (PMID 34362877, 2021). "SYK functions as a signaling hub within the CLR signaling complex whose activity needs to be tightly controlled during fungal infections." (PMID 39471181, 2024). "The signalling axis of β-glucan, DECTIN-1, SYK and CARD9 is a central pillar of inflammasome activation, as well as the release of inflammasome/pyroptosis-associated IL-1β and IL-18 in fungal infection and beyond." (PMID 38515333, 2024). "In this study, we screened several important members of the TRIM family to investigate the possible roles of this family in regulating SYK activity during fungal infections." (PMID 34362877, 2021). "As an essential adaptor and kinase of the CLR signaling complex proximal to the plasma membrane, SYK activity must be fine-tuned during fungal infection." (PMID 34362877, 2021). "To investigate CIN’s immunomodulatory mechanism, we analyzed Dectin-1 signaling components (Dectin-1, SYK, and CARD9), NF-κB activation, and proinflammatory cytokines (TNF-α and IL-1β) in RAW264.7 and PMA-differentiated THP-1 macrophages during a 24-h fungal infection." (PMID 41031111, 2025). "In summary, we identified a previously unknown role for VCP in the activation of SYK and antifungal immune responses and propose VCP as a potential drug target in treating fungal infections." (PMID 39471181, 2024). "SYK controls both pro-IL-1β synthesis and NLRP3 activation in response to fungal infection." (PMID 38992615, 2024).
ischemic stroke (10 papers, 2019 to 2024). A stroke disorder caused by obstruction of blood flow to the brain, due to thrombotic (local blood clot formation) or embolic (due to a blood clot or other material traveling from another site) event. "Spleen tyrosine kinase (SYK) gene has been identified as novel susceptibility locus for ischaemic stroke (IS) previously." (PMID 30499219, 2019). "In contrast, TREM1 mediates neuroinflammation during an ischemic stroke by interacting with the spleen tyrosine kinase (SYK) signaling pathway and activating downstream nuclear factor kappaB (NF‐κB) and NLRP3 inflammasome." (PMID 38680509, 2023). "In contrast, TREM1 mediates neuroinflammation in ischemic stroke by interacting with the SYK signaling pathway to activate downstream NF‐κB and NLRP3 inflammasome." (PMID 38680509, 2023). "Among the gene targets of miR-486-3p, FASN has been reported as a critical mediator in de novo lipogenesis in astrocytes following cerebral ischemic injury, while SYK is involved in cerebral inflammatory activation after ischemic stroke." (PMID 36613546, 2022). "The potential role of mir-129-2-3p in ischemic stroke was identified by suppressing SYK gene expression." (PMID 36605987, 2022). "Microglia are also highly expressed in TREM1 upon activation, which can mediate neuroinflammation in ischemic stroke by interacting with the spleen tyrosine kinase (SYK) signaling pathway, activating downstream NF‐κB and nucleotide‐binding oligomerization domain (NLRP3) inflammasomes." (PMID 39691417, 2024). "In an ischemic stroke model, mTrem1 activated the NF-κB signaling pathway and NLRP3 inflammasome via its interaction with SYK in microglia." (PMID 36068612, 2022). "In experimental ischemic stroke, TREM-1 acts by activating the pro-inflammatory pathways NF-κB and inflammasome (NLRP3)/caspase-1, which occurs through interacting with spleen tyrosine kinase (SYK)." (PMID 31546668, 2019). "Moreover, in animal ischemic stroke experiments, microglial TREM-1 induced the activation of spleen tyrosine kinase (SYK), which increased the level of the N-terminal fragment of GSDMD." (PMID 36582214, 2022). "SYK inhibitor R406 significantly deactivated NLRP3, Caspase-1, and GSDMD-N signaling; reduced the concentration of IL-1β; and attenuated GSDMD-N induced membrane pores in mice with ischemic stroke." (PMID 33402173, 2021).
lupus (10 papers, 2013 to 2025). "Accordingly, the spleen tyrosine kinase (SYK) plays a crucial role in various signaling pathways of inflammation, especially in lupus dysregulated inflammation, due to CIC and microbial molecules from the gut." (PMID 39962056, 2025). "Increased SYK phosphorylation after BCR cross‐linking was found in peripheral blood B cells of patients with active systemic lupus erythematosus (SLE)." (PMID 37506139, 2023). "While the impact of NETs-SYK and NETs-p38MAPK in SLE is well-known, data on the signaling of METs in lupus is still limited." (PMID 39962056, 2025). "This is an important finding considering celastrol can downregulate the signaling cascade of the SYK-MEK-ERK-NFkB, and the downregulation of IL-12 p40 (which correlates negatively with lupus SLE activity), which ultimately contributes to excessive IL-10 (positively correlated with lupus pathology)." (PMID 35431950, 2022). "Other therapies which target molecules believed to play a role in CLE pathogenesis, such as Janus kinases (JAKs), spleen tyrosine kinase (SYK), interferon γ (IFNγ), IL-12, and IL-23, have been evaluated in lupus clinical trials with skin-specific outcomes but failed to meet their primary endpoints." (PMID 35899214, 2022).
Alzheimer disease (9 papers, 2017 to 2025). A progressive, neurodegenerative disease characterized by loss of function and death of nerve cells in several areas of the brain leading to loss of cognitive function such as memory and language. "Conversely, the inhibition or genetic deletion of SYK impairs this clearance mechanism, leading to exacerbated amyloid pathology and cognitive decline in 5-familial Alzheimer’s disease mutations (5xFAD) mice and SYK mice models." (PMID 40650013, 2025). "The reproducibility of tyrosine-protein kinase SYK research would help elucidate the mechanism in which it causes neuroinflammation as well as its potential as a novel target to treat Alzheimer’s disease." (PMID 38948505, 2023). "Spleen tyrosine kinase (SYK), the fourth ranked potential target, could modulate the accumulation of amyloid- β and hyperphosphorylation of Tau protein, which is associated with Alzheimer’s disease." (PMID 33941241, 2021). "Recent research has elucidated that TREM2 facilitates the microglial response to amyloid-beta through independent and spleen tyrosine kinase (SYK)-dependent mechanisms, as evidenced in the 5xFAD model of Alzheimer’s disease." (PMID 39596378, 2024). "RNA sequencing and genetic data support spleen tyrosine kinase (SYK) and high affinity immunoglobulin epsilon receptor subunit gamma (FCER1G) as putative targets to be modulated for Alzheimer’s disease (AD) therapy." (PMID 38359047, 2024). "We applied our computational framework to prioritize novel putative target genes for Alzheimer’s disease and successfully identified key genes that may serve as novel therapeutic targets (e.g., DLG4, EGFR, RAC1, SYK, PTK2B, SOCS1)." (PMID 33941241, 2021).
hepatocellular carcinoma (8 papers, 2017 to 2025). A malignant tumor that arises from hepatocytes. "Therefore, both full-length SYK and SYK-S are regarded as diagnostic and prognostic makers in human hepatocellular carcinoma." (PMID 36568669, 2022). "Hypoxia suppressed the Siglec-5 signaling in TAMs via modulating the balance of SHP2/SYK activation in hepatocellular carcinoma." (PMID 40858654, 2025). "SHP-1 and SHP-2 regulate SYK dephosphorylation through interactions with Siglec-5 and SIRPα, influencing cell signaling pathways and hepatocellular carcinoma progression." (PMID 40858654, 2025). "The interactions among Siglec-5, Siglec-14, SIRPα, SHP1, SHP2, SYK, and ROS create a complex regulatory network in hepatocellular carcinoma." (PMID 40858654, 2025). "Totally, the accurate position of SYK in hepatocellular carcinomas is still in controversial although some SYK inhibitors have showed the therapeutic effect against human hepatocarcinogenesis." (PMID 36568669, 2022). "Using proximity biotinylation assays, we identified SYK (spleen tyrosine kinase) as a kinase involved in DEPTOR Tyr 289 phosphorylation in an ephrin (erythropoietin-producing hepatocellular carcinoma) receptor–dependent manner." (PMID 34634301, 2021). "For instance, in patients with hepatocellular cancer, the expression of SYK(S) has been reported to be a significant indicator of poor prognosis." (PMID 28957395, 2017). "Specifically, members of the sialic acid-binding immunoglobulin-like lectin (Siglec) family, signaling molecules such as SHP1, SHP2, and SYK, and oxidative stress-related factors like ROS play key roles in the initiation and development of hepatocellular carcinoma." (PMID 40858654, 2025). "Particularly in hepatocellular carcinoma, the Siglec-14/SYK signaling pathway may participate in the progression of hepatocellular carcinoma by modulating inflammatory responses and the immune microenvironment." (PMID 40858654, 2025). "In addition, the raw letter suggested that ROS was positively correlated with SYK, and the experimental hypoxic conditions significantly increased the P-SYK level, further supporting the role of the ROS-SYK axis in hepatocellular carcinoma." (PMID 40858654, 2025). "In addition, several groups have confirmed the therapeutic action of SYK inhibitors against hepatocellular carcinoma." (PMID 36568669, 2022). "In addition, the relationship between SYK and hepatocellular carcinoma has been clarified gradually in recent years." (PMID 36568669, 2022). "Robust SYK expression has been discovered in hepatocytes, hepatic stellate cells, as well as Kupffer cells, which participates in the regulation of numerous signal transduction in various liver diseases (e.g. hepatitis, liver fibrosis and hepatocellular carcinoma)." (PMID 36568669, 2022). "In recent years, some studies also indicated that SYK joins in the regulation of PI3K/Akt signaling pathway, which hold a key role in CX3CL1-induced platelet migration as well as cell apoptosis in human hepatocellular carcinomas." (PMID 36568669, 2022). "In addition, the activation of SYK also can be positively regulated by CD81, a member of the tetraspanin protein family, which promotes the development of hepatocellular carcinomas." (PMID 36568669, 2022). "The full-length SYK inhibits metastasis in hepatocellular carcinoma, while the SYK-S lacking 23 amino acids in the IDB, promotes the growth and invasion of hepatocellular carcinoma." (PMID 36568669, 2022). "Some researchers showed that the patients with negative expression of SYK in hepatocellular carcinoma hold lower overall survival rate, compared with the patients with positive expression of SYK." (PMID 36568669, 2022).